ICAM1 (intercellular adhesion molecule 1)
Diseases named in the same sentence as ICAM1 in open-access papers (continued):
Sharing a sentence is not in itself a finding about the gene and the disease.
tumor (continued). "Our verification studies showed that ICAM1 mRNA was expressed at higher level in tumor compared to the adjacent normal breast tissue." (PMID 30082828, 2018). "The extravasation of T cells into the tumor tissue depends on the expression levels and clustering patterns of intercellular adhesion molecule-1 (ICAM-1) and vascular cell adhesion molecule-1 (VCAM-1)." (PMID 29774034, 2018). "In the same sense, the amount of T-lymphocytes that remained in the tumor tissue was significantly decreased in anti-ICAM-1 treated mice." (PMID 30258446, 2018). "EWS-FLI1 ‘low’ cells demonstrated a significant decrease in T-cell mediated tumor cell apoptosis upon introduction of ICAM-1 blocking antibody." (PMID 30400822, 2018). "The specificity of UniPR1331 for the Eph-ephrin system was evaluated by testing the compound on several targets promoting tumor angiogenesis (ICAM-1, PDGFR, and FGFR) and proliferation (TGF-β, EGFR)." (PMID 29849945, 2018). "Direct in vivo testing indicated that CD8+ T-cells pre-cultured for 7 days on substrate-immobilized CCL21 + ICAM1 suppressed tumor growth to a significantly greater extent than T-cells cultured on unmodified substrates." (PMID 29942308, 2018). "First, it is important to bear in mind that long term interference with LFA-1/ICAM-1 interactions would disrupt critical immune synapses and the entrance of leukocytes into the tumor from the bloodstream." (PMID 30258446, 2018). "ICAM1 immunoreactivity was mainly localized in the cell membrane of the tumor cells, but different staining patterns of ICAM1 were observed." (PMID 30082828, 2018). "The limitation of this study was that only two signals out of ~20 signals (expressed only by invasive tumor cells) from the proteomic analysis was validated (ICAM-1 and TGFβ2)." (PMID 29966014, 2018). "While the enhanced cytotoxicity of T-cells cultured on CCL21 + ICAM1 toward cultured cancer cells was compelling, we further tested their capacity to kill tumor cells in vivo." (PMID 29942308, 2018). "To test this, we first detected by flow cytometry the intensity of ICAM-1 expression on the surface of tumor cells." (PMID 30258446, 2018). "Conversely, ICAM1 has also been proposed to be involved in tumor cell invasion and migration into secondary sites." (PMID 30082828, 2018). "It is important to mention that the percentage of tumor cells that expressed ICAM1 ranged from less than 10 to 100% with intertumoral differences in staining patterns." (PMID 30082828, 2018). "Binding of these integrins to their ligands, like VCAM-1 and ICAM-1, present on tumor vasculature leads to a firm arrest of leukocyte motion." (PMID 30386740, 2018). "Proton radiation and photon radiation upregulate surface cell molecules, such as ICAM1, HLA, the tumor-associated antigens MUC-1 and CEA, and calreticulin, to comparable extents, increasing the killing of tumor tissue by T cells." (PMID 30487462, 2018). "The interaction of neutrophil integrin CD11b (also known as ITGAM) with intercellular adhesion molecule 1 (ICAM-1) on cancer cells and platelet-induced clot formation further promote tumor cell adhesion." (PMID 30355585, 2018). "It has been shown that ICAM-1 expressed on the tumor cells binds to LFA-1 on CD8+ T cells and promotes activation and cytotoxicity of CD8+ T cells in a TCR-dependent fashion." (PMID 29966014, 2018). "IFN sensitive (IFN inhibits protein translation and virus replication but in tumor cells this protein translational block is impaired) Receptor tropism: CVA21 infects by ICAM-1 as primary receptor and DAF as coreceptor." (PMID 30405639, 2018). "Senescent mesothelial cells change the cellular signaling in the tumor microenvironment, expressing factors such as fibronectin, intercellular adhesion molecule-1 (ICAM-1), beta-galactosidase and thymosin beta-10." (PMID 29996539, 2018).
tumor (continued). "Our in vivo findings correlated with those found in vitro and show that OT-I T-cells pre-cultured on substrate-immobilized CCL21 + ICAM1, suppressed tumor growth to a significantly greater extent than those pre-cultured on an uncoated substrate." (PMID 29942308, 2018). "Hyperthermia hase been shown to modify the tumor vasculature by upregulating the adhesion of molecules E/P-selectins and ICAM-1 expression by inducing IL-6 trans-signalling on the endothelium." (PMID 30126117, 2018). "Several NK cell ligands were upregulated, but the results of that study suggested that the effect of IFN-γ on NK cell-mediated lysis of tumor cells was mainly associated with changes in MHC-I and ICAM-1 expression." (PMID 30294328, 2018). "As a novel synergistic tumor immune escape was exerted by ICAM-1 and TGFβ2 signal, it opens a new potential in translational application." (PMID 29966014, 2018). "Analyses of the ICAM1 immunoreactivity in these tumor specimens revealed positive staining in endothelial cells, lymphocytes in stroma, and macrophages." (PMID 30082828, 2018). "When the glioma stem cell line GSC11 was subjected to hypoxic conditions, HIF-1-induced phosphorylated STAT3 activated ICAM-1 transcription and promoted macrophage infiltration into the tumor tissues." (PMID 29670046, 2018). "This likely involves a diminished cytotoxic response of LSLs, mediated by endothelial ManR, whose activity, in turn, depends on the interaction of ICAM-1 on LSEC with the tumor β2 integrin." (PMID 29207960, 2017). "This process is known to be altered on LSECs after direct endothelial ICAM-1/tumor LFA-1 interaction and abolished after the binding of those two adhesion molecules is blocked." (PMID 29207960, 2017). "Consistent with the finding in the tumor samples, ECM components and mechanics-associated genes (from PLOD2 to ICAM1) were upregulated in ccRCC patients as shown by the ‘TME PCR Array’." (PMID 28846080, 2017). "More importantly, we found that mice bearing tumor with ICAM-1 knockdown had a prolongation of overall survival compared to control tumor bearing mice." (PMID 29228586, 2017). "We first confirmed that ICAM-1 is induced by both LIF and TGFβ and showed that ICAM-1 expression in hDF is stimulated by tumor cells conditioned media." (PMID 27901489, 2017). "In previous studies, we reported that the ligation of LFA-1 expressed on tumor cells with endothelial ICAM-1 induced the production of ManR-stimulating factors from C26 cells, including IL-1, VEGF and sICAM-1, mediated by the activity of COX-2 in tumor cells." (PMID 29207960, 2017). "We have identified a novel role for ICAM-1, an inflammatory responsive gene, in the establishment of a protumorigenic tumor stroma." (PMID 27901489, 2017). "In contrast, in some reports, the expression of ICAM-1 has been positively correlated with a more aggressive tumor phenotype and metastatic potential." (PMID 29099772, 2017). "ICAM-1 is an inducible adhesion molecule that is sensitive to inflammatory stimuli and the tumor-related inflammatory milieu." (PMID 29085043, 2017). "We demonstrate that membrane-bound ICAM-1 promotes inflammation-dependent extracellular matrix remodeling, which leads to tumor cell dissemination." (PMID 27901489, 2017). "ICAM-1 was found to influence tumor progression and metastasis, whereas FBXO4 regulated aggressive tumorigenic conditions." (PMID 29137327, 2017). "miR-192 impairs angiogenesis and reduces bone colonization of tumor cells by downregulating the expression of proangiogenic intercellular adhesion molecule 1 (ICAM-1), IL-8 and chemokine ligand 1 (CXCL1)." (PMID 29302403, 2017). "The production of prostaglandin E2 in the tumor microenvironment limits the expression of ICAM-1 in tumor cells, reducing the cytotoxic effectivity of T cells." (PMID 29099772, 2017).
tumor (continued). "Based on these findings, we investigated ICAM1 protein localization and expression in tumor tissue sections from the subcutaneous (s.c.)experiment, which confirmed reduced levels of both proteins in situ." (PMID 28415753, 2017). "In reaction to inflammatory signaling cues, fibroblasts populating the tumor stroma are activated, which induces ICAM-1 expression at the cell surface." (PMID 27901489, 2017). "To further elucidate the relationship between ICAM-1 expression in tumor cells and macrophage infiltration, we performed an in vitro cell binding assay." (PMID 29228586, 2017). "Activation of ICAM-1 expression on endothelial surfaces in tumor was also shown to play a role in metastasis formation." (PMID 29340117, 2017). "The first ICAM-1 antibody tested against human tumor cells was UV3 developed by the group of Ellen Vitettta in 1993." (PMID 29100408, 2017). "Overexpression of ICAM-1 in cancer tissues, both in tumor cells and stroma, has previously been reported." (PMID 27901489, 2017). "tHSCs are tumor-promoting cells, which express intercellular adhesion molecule 1 (ICAM-1) and vascular cell adhesion molecule 1 (VCAM-1) among other factors to promote cancer cell migration and proliferation." (PMID 28903404, 2017). "Adherence between neutrophil cell surface ligands and tumor-expressed ICAM-1 stimulates neutrophil degranulation releasing elastases, which break down endovascular and endolymphatic barriers permitting transendothelial tumor cell migration." (PMID 29340117, 2017). "Endothelial ICAM1 is one of the key adhesion molecules that mediate leukocyte rolling and adhesion, and hence contributes to leukocyte infiltration and anti-tumor immunity." (PMID 28951988, 2017). "Small tumor volume correlated with low ICAM-1 expression level (as assessed by immunofluorescence) in the shICAM-1 #4 group compared with the parental GSC11 group." (PMID 29228586, 2017). "In the present study, we found that ICAM-1 knockdown reduced macrophage infiltration into tumor in vivo and that an anti–ICAM-1 antibody inhibited tumor cells from migrating to macrophages in vitro." (PMID 29228586, 2017). "Adhesion molecules such as ICAM-1 are regulated by NF-κB and are essential for the adhesion of tumor cells to endothelial cells, and thus mediate tumor cell metastasis." (PMID 28933726, 2017). "In light of these data we confirmed that membrane-bound ICAM-1 regulates the onset of a proinvasive tumor microenvironment potential in CAF by regulation of the acto-myosin cytoskeleton contractility." (PMID 27901489, 2017). "There is no clear explanation for the apparently contrary roles played by ICAM-1 in tumor development, suggesting that the function of ICAM-1 is context dependent: modulated by the simultaneous action of other membrane receptors." (PMID 29099772, 2017). "Many studies have shown that various cancer cells, including breast, bladder, pancreatic, and oral cancer cells and cells within the tumor environment, overexpress ICAM-1." (PMID 28417928, 2017). "Overexpression of ICAM-1 has been demonstrated to be involved in immune surveillance in breast, gastric, and colorectal cancers, but it was shown to promote tumor growth, progression, and angiogenesis in oral cancer." (PMID 29250531, 2017). "ICAM-1 is a transmembrane molecule involved in many important processes and has recently been reported to be involved in tumor progression, abnormality, and malignant phenotypes." (PMID 29137327, 2017). "In this review, we summarize the studies relating LFA-1 and its major ligand ICAM-1 (or CD54) with cancer, through the function of lymphocytes and myeloid cells on tumor cells." (PMID 29099772, 2017). "Such interaction is mediated by the β2 integrins on neutrophils that bind to ICAM-1 on tumor cells and was described for liver and lung metastasis model." (PMID 29340117, 2017).
tumor (continued). "Based on these findings, we fluorescently stained the tumor section of our first subcutaneous model (as previously detailed) with anti-ICAM1 antibody." (PMID 28415753, 2017). "We show that suppression of BRD7 induces a pro-angiogenic cytokine and gene expression profile, whereas increased expression of BRD7 induces NFκB-mediated ICAM1 expression which promotes anti-tumor immunity." (PMID 28951988, 2017). "ICAM-1 upregulation resulted in increased conjugate formation between the NK cells and tumor cells, which can contribute to the increased sensitivity observed." (PMID 28428785, 2017). "Knocking down ICAM-1 suppressed tumor invasion in vitro and in vivo and inhibited macrophage infiltration to the tumor site in bevacizumab-treated mice." (PMID 29228586, 2017). "Additional feature observed in HUVECs knocked down of PKN3 was defective glycosylation of ICAM-1, a central adhesion molecule important for binding and signaling between vascular endothelial cells and tumor cells during the tumor metastasis." (PMID 26742562, 2016). "HRS cells also secrete lymphotoxin-α (LTα), which stimulates endothelial cells to upregulate ICAM-1 and hyaluronan levels to enhance recruitment of T cells into the tumor milieu." (PMID 27563824, 2016). "Based on these observations, the impact of specific GPs and SeGPs on expression of ICAM-1 in brain microvessels appears to be dependent on the stage of tumor growth." (PMID 26706037, 2016). "Interesting results were observed when analyzing the impact of GP40 supplementation on tumor cell-induced upregulation of ICAM-1." (PMID 26706037, 2016). "VEGF-A and bFGF, also a strong mitogenic factor for endothelium produced by tumor cells, contribute to the suppression of ICAM-1 in tumors." (PMID 28066431, 2016). "NK cell production of IFN-γ has been reported to augment cytotoxic activity by up-regulating expression of the adhesion molecule ICAM-1 on tumour target cells through the NF-κβ pathway which improves conjugate formation and adherence with cytotoxic NK cells." (PMID 27098723, 2016). "Assessing levels of a combination of biomarkers such as NF-κB, sCD30, and ICAM-1 in pediatric HL patients would be helpful to gain insight into disease progression throughout the course of tumor management." (PMID 27563824, 2016). "GP40 was the only fraction which protected against ICAM-1 mRNA increase 48 h post tumor cell infusion." (PMID 26706037, 2016). "At the same time, leukocyte function associated protein 1 (LFA-1, also known as CD11a-CD18 and αLβ2), a cognate ligand to ICAM-1, was also strongly upregulated, particularly on tumour cells." (PMID 27447568, 2016). "ICAM1 was found to be less relevant in tumour cell adhesion in the context of peritoneal metastases." (PMID 27074785, 2016). "There was also a significant interaction between diets and tumor cell infusion on ICAM-1 mRNA expression at 48 hr." (PMID 26706037, 2016). "The intercommunication between LFA-1 on tumour cells and ICAM-1 (or alternative ligands, ICAM-2/ICAM-3/ICAM-4/JAM-1) on other cells in the local vicinity triggers signalling through several pathways on each side." (PMID 27447568, 2016). "Different neutrophil-mediated mechanisms of metastatic spread are described, including promotion of tumor cell extravasation by binding ICAM-1 on tumor cells or by catching tumor cells via NETs." (PMID 28066438, 2016). "The effects of selenoglycoproteins and tumor cell infusion on the expression of selected cell adhesion molecules, namely ICAM-1, VCAM-1, and ALCAM, were evaluated by quantitative reverse transcription PCR." (PMID 26706037, 2016). "For the tumor, an up-regulation of NFκB target genes was observed (e.g. IL-6, IL-8, ICAM1) as well as of cytokines typically expressed by epithelial cells or fibroblasts involved in the first events of an immune response." (PMID 27463372, 2016).
tumor (continued). "Infusion of tumor cells significantly upregulated ICAM-1 mRNA levels within all dietary treatments except for GP40 (48-h time point) and SeGP65 (3 week time point)." (PMID 26706037, 2016). "Tumor-specific forms of MUC1 promote tumor cell adhesion to the endothelium through interactions with E-selectin and the intercellular adhesion molecule-1 (ICAM-1), two receptors expressed on the surface of endothelial and peritumoral stromal cells." (PMID 27754373, 2016). "To determine the contribution of macrophages to tumor development, we characterized cells expressing Mac-2 (the macrophage marker) in both WT and ICAM-1−/− mice." (PMID 26068788, 2015). "12-O-tetradecanoylphorbol-13-acetate (TPA) acts as a tumor promoter that induces the expression of ICAM-1 in many types of cells." (PMID 26087182, 2015). "Direct cell-cell interaction of neutrophils with breast carcinoma cells has been shown to involve the adhesion molecule ICAM-1 on the tumor cells and β2 integrins on neutrophils." (PMID 26819959, 2015). "We next performed tumor cell binding assays in the presence of neutralizing antibodies against E-selectin, ICAM-1 or VCAM-1 to investigate the role these adhesion molecules in tumor cell binding." (PMID 26509633, 2015). "Lipid and vessel staining revealed that tissue lipid levels were lower in vessel-poor regions in ICAM1-positive xenograft tumor tissues, suggesting a directly proportional correlation between lipid contents and vessel densities." (PMID 25879517, 2015). "ICAM-1 is constitutively over-expressed in many carcinomas including breast, colon, non-small cell lung, and gastric tumors, and in tumor stroma within an inflammatory network." (PMID 25901755, 2015). "Others have also shown a role for ICAM-1 during tumor metastasis, particularly invasion and migration." (PMID 26231039, 2015). "ICAM-1−/− macrophages demonstrated significantly higher phagocytosis of apoptotic tumor cells than WT macrophages." (PMID 26068788, 2015). "ICAM-1 was shown to be mechanistically involved in these inhibitors’ ability to sensitize tumor cells to immune-mediated attack by functional blocking studies." (PMID 26579226, 2015). "To assess the functional phagocytic activities, we cocultured apoptotic tumor cells with WT and ICAM-1−/− BMDMs and engulfment of fluorescent ACs was determined." (PMID 26068788, 2015). "In all tumor cells investigated the ICAM-1 antibody significantly suppressed the celecoxib-induced tumor cell lysis by LAK cells when compared to cells treated with vehicle and isotype control antibody, respectively." (PMID 26513172, 2015). "The ICAM-1 expression analysis also confirmed the pro-tumor role of colorectal M2 macrophages in carcinoma progression and metastasis." (PMID 25434400, 2015). "The LFA-1 heterodimer (CD11a/CD18) is the natural ligand of ICAM-1 that has been reported to represent an important link to conjugate ICAM-1-bearing cells with natural killer cells and to confer lymphocyte-induced tumor cell killing." (PMID 26513172, 2015). "This suggests a possibly predominant contribution of stroma-derived ICAM-1 as a tumor metastasis suppressor." (PMID 26068788, 2015). "ICAM-1 also correlated significantly with the proportion of tumor-infiltrating leukocytes, including macrophages." (PMID 26231039, 2015). "In additional, ICAM1 is known to be overexpressed in cancer cells where it recruits immune cells to promote tumor progression." (PMID 25879517, 2015). "Consistent with tumor volume, both HO-1 protein and ICAM-1 protein expression levels differed between enucleated tumors, as measured by western blot analysis." (PMID 26087182, 2015). "Because ICAM-1 has been reported to play an important role in the interaction between tumor cells and host cytotoxic effector cells, we evaluated the effects of HO-1 on the adhesion of PBMLs to CRC cells." (PMID 26087182, 2015).